CCL5 (C-C motif chemokine ligand 5)
Diseases named in the same sentence as CCL5 in open-access papers (continued):
Sharing a sentence is not in itself a finding about the gene and the disease.
prostate carcinoma (continued). "In prostate cancer cell lines, CCL5 enhanced the proportion of stem cells (CD133+ cells) in cell populations and promoted sphere formation." (PMID 24502410, 2014). "Co-cultures of prostate cancer cells and BM-MSCs significantly increased the secretion of CCL5 by BM-MSCs." (PMID 24502410, 2014). "Chronic inflammation is associated with CXCL12, CCL5, and CCL2, which are highly overexpressed in prostate cancer." (PMID 23362217, 2013). "Recently, the chemochine CCL5 (RANTES) was found to be expressed by human prostate carcinoma cells and reported to stimulate their proliferation and invasion." (PMID 19242540, 2009). "Additionally, pomegranate juice significantly reduced the level of secreted IL-6, IL-12p40, IL-1β and CCL5 (C-C motif chemokine ligand 5) in prostate cancer cells." (PMID 39683144, 2024). "Interestingly, TAMs secrete CCL5 that promotes self‐renewal of prostate cancer stem cells (PCSCs) and enhances migration, invasion, and metastasis of prostate cancer cells by the activation of the β‐catenin/STAT3 signaling pathway." (PMID 38703051, 2024). "Using a coculture of C4-2 cells, a metastatic prostate cancer cell line, and human umbilical vein endothelial cells (HU-VEC), the authors show that HUVEC enhanced prostate cancer cell invasion by decreasing androgen receptor (AR) activity in a C-C chemokine ligand type 5 (CCL5)- dependent manner." (PMID 39082334, 2024). "In prostate cancer, CCL5 derived from macrophages can promote the metastasis of prostate cancer." (PMID 37715019, 2023). "In addition, CCL5 derived from TAMs has been reported to increase the stemness and metastatic capacity of prostate cancer cells." (PMID 36766725, 2023). "Furthermore, CCL5 expression was significantly increased in prostate cancer tissue samples and was correlated with higher Gleason scores." (PMID 36836690, 2023). "Furthermore, blockade of CCL5 reversed this low sensitivity, indicating the effect of CCL5 in promoting prostate cancer cell survival in response to docetaxel." (PMID 36836690, 2023). "Moreover, M2 macrophages were found to secrete chemokine CCL5, which promotes prostate cancer cell invasion, migration, and EMT via activating β-catenin/STAT3 pathway, whereas CCL5 knockdown suppresses tumor growth and bone metastases." (PMID 35994202, 2022). "Importantly, previous studies in lung, ovarian and prostate cancers have shown elevated levels of CCL5 secreted by CAFs, which led to therapy resistance and cancer cell survival." (PMID 35954489, 2022). "In the present study, we demonstrated that high CCL5 expression was significantly correlated with high Gleason grade, poor prognosis, metastasis as well as increased PCSCs activity in prostate cancer patients by conducting clinical investigations and bioinformatic analysis." (PMID 32300100, 2020). "However, the role and prognosis significance of CCL5 in prostate cancer have been rarely reported so far, and little is known about the influence of TAMs-secreted CCL5 on PCSCs." (PMID 32300100, 2020). "Notably, CCL5 knockdown in TAMs not only significantly suppressed prostate cancer xenografts growth and bone metastasis but also inhibited the self-renewal and tumorigenicity of PCSCs in vivo." (PMID 32300100, 2020). "Nevertheless, the prognostic value of TAMs-secreted CCL5 for prostate cancer as well as its modulatory effect on both prostate cancer cells and PCSCs cells remain unclear and deserve further investigations." (PMID 32300100, 2020). "Finally, clinical investigations and bioinformatic analysis suggested that high CCL5 expression was significantly correlated with high Gleason grade, poor prognosis, metastasis as well as increased PCSCs activity in prostate cancer patients." (PMID 32300100, 2020). "Altogether, high CCL5 expression may predict poor prognosis and increased PCSCs activities in prostate cancer patients." (PMID 32300100, 2020).
prostate carcinoma (continued). "Furthermore, CCL5 treatment also significantly induced the expression and nuclear translocation of β-catenin in prostate cancer cells." (PMID 32300100, 2020). "Taken together, TAMs/CCL5 could promote PCSCs self-renewal and prostate cancer metastasis via activating β-catenin/STAT3 signaling." (PMID 32300100, 2020). "Additionally, CCL5 overexpression was observed in prostate cancer tissues when compared with para-carcinoma tissues (p < 0.05)." (PMID 32300100, 2020). "More importantly, CCL5 knockdown in TAMs could dramatically suppress PCSCs self-renewal and prostate cancer growth and metastasis." (PMID 32300100, 2020). "Altogether, CCL5 knockdown in TAMs could suppress prostate cancer xenografts growth, bone metastasis as well as PCSCs self-renewal and tumorigenicity in vivo." (PMID 32300100, 2020). "Furthermore, castration-resistant prostate cancer patients also exhibited increased CCL5 expression when compared with patients with good prognosis (p = 0.042)." (PMID 32300100, 2020). "This study not only uncovers the modulatory mechanism of TAMs/CCL5 in promoting PCSCs self-renewal and prostate cancer metastasis but also provides a novel rationale for developing TAMs/CCL5 as a potential molecular target for PCSCs elimination and metastatic prostate cancer prevention." (PMID 32300100, 2020). "In summary, the present study demonstrates that TAMs-secreted CCL5 could promote PCSCs self-renewal and prostate cancer metastasis via activating β-catenin/STAT3 signaling." (PMID 32300100, 2020). "Altogether, these results indicated that CCL5 could promote prostate cancer invasion and PCSCs self-renewal via activating the CCR5/β-catenin/STAT3 pathway." (PMID 32300100, 2020). "In addition, CCL5 silencing in TAMs significantly inhibited prostate cancer xenografts growth, bone metastasis as well as PCSCs self-renewal and tumorigenicity in vivo." (PMID 32300100, 2020). "CCL5 secreted by prostate cancer cells induces the migration of MSCs." (PMID 32630699, 2020). "CCL5 secreted by T cells decreases chemotherapy activity in prostate cancer." (PMID 32630699, 2020). "In breast, ovarian and prostate cancer, CCL5 secreted by the TME can reduce drug activity." (PMID 32630699, 2020). "RNA-sequencing and mechanistic explorations further revealed that CCL5 could promote PCSCs self-renewal and prostate cancer metastasis via activating the β-catenin/STAT3 signaling." (PMID 32300100, 2020). "As CCL5 was unable to promote migration of LNCaP siAR cells, it was concluded that elevated CCL5 secretion by bone stromal cells from metastatic lesions induced prostate cancer cell migration in a CCL5-dependent manner, upstream of AR signaling." (PMID 30871130, 2019). "Estrogen receptor α could reduce prostate cancer cell invasion through reduction of CCL5 secretion from fibroblasts and macrophage infiltration prostate cancer." (PMID 30871130, 2019). "Here, as CCL5 is the most significantly secreted factor by endothelial cells, we are the first to demonstrate CCL5 may be one of the key factors contributing to improving invasion of prostate cancer cells." (PMID 30200999, 2018). "Together, these results indicate that CCL5 released by endothelial cells may be the essential factor to induce AR downregulation and consequently increase invasion ability of prostate cancer." (PMID 30200999, 2018). "qPCR validation of CCL5 in prostate cancer cells or HUVEC after transfecting siCCL5 for 72 h; B." (PMID 30200999, 2018). "In addition, the effects of CCL5 on gastric, ovarian, and prostate cancer occurrence and metastasis were widely studied, while the mechanisms of CCL5 expressed by MSCs on CCA cells migration and invasion are poorly understood." (PMID 29088737, 2017). "Additionally, CCL5 expression is upregulated in MSCs from prostate cancer and breast cancer cell lines." (PMID 24502410, 2014).
prostate carcinoma (continued). "Five SNPs detected in CCL5, CCR5 and CCR7 were significantly associated with prostate cancer risk among all study participants; however, only three markers survived adjustments for potential confounders and multiple hypothesis testing." (PMID 23168091, 2012). "As a result of pooling, we identified three SNPs (i.e., CCL5 rs3817655, CCL5 rs2107538, CCR5 rs1799988) that were significantly associated with prostate cancer in the total population even after adjusting for age and multiple hypothesis testing." (PMID 23168091, 2012). "RANTES (CCL5) is an important member of the CC subfamily of chemokines, which has an important role in promoting proliferation, angiogenesis, metastasis and drug resistance of prostate cancer cells via its crosslinking with chemokine (C-C motif) receptor 5 (CCR5) or CCR1." (PMID 35804830, 2022). "Western blotting assay further indicated that CCL5 could induce epithelial-mesenchymal transition (EMT) in both prostate cancer cells, characterized by the decreased expression of E-cadherin as well as the increased expression of N-cadherin, Vimentin, MMP2, and MMP9." (PMID 32300100, 2020). "Finally, the clinical significance of CCL5 for prostate cancer patients was investigated." (PMID 32300100, 2020). "Interaction between CCR1 and CCL5 promotes the invasion of taxane-resistant PC3 prostate cancer cells by increasing the secretion of MMP-2 and -9 via ERK and Rac activation suggesting that CCR1 could be a novel therapeutic target for taxane-resistant prostate cancer." (PMID 24523569, 2014). "Thus, also CCL5 appears to be directly involved in the behaviour of prostate carcinoma cells." (PMID 19242540, 2009). "Further, immunosuppressive TAMs secrete CCL5, which activates STAT3 signaling and promotes stem-like features and drug resistance in prostate cancer." (PMID 41228234, 2025). "CCL5 signaling through beta-catenin/signal transducers and activators of transcription 3 (STAT3) promotes both metastasis and drug resistance in prostate cancer." (PMID 40076892, 2025). "CCL5 belongs to the family of C-C chemokines as do CCL7, CCL8, and CCL21, which were also upregulated in prostate cancer lung metastases." (PMID 39146303, 2024). "This supported their conclusion that CCL5, CCLR5 and/or autophagy are potential drug targets to inhibit endothelial cell promotion of prostate cancer metastases." (PMID 39082334, 2024). "Results from the migration assays showed that mast cell migration was mediated via various chemokines including SCF, CCL5 and CCL11 secreted by PKD2/3 expressed-prostate cancer cells." (PMID 36836690, 2023). "Both CCL5 and CCL2 have been shown to enhance the migratory abilities of prostate cancer cells ultimately contributing to their migration to other parts of the body including to the bone, the most common site of prostate cancer metastasis." (PMID 36836690, 2023). "Huang reported that TAMs produce CCL5, which activates the I-CATENIN/STAT3 pathway, potentially contributing to prostate cancer stem cell survival and metastasis." (PMID 36825082, 2023). "Tumor associated macrophages (TAMs) secrete pro-inflammatory cytokines such as CCL5 and CCL2 which greatly affect the progression of prostate cancer and prostate cancer metastasis." (PMID 36836690, 2023). "This may also be of use in the studying diseases such as prostate cancer where it has been shown that an increase of 40 mmHg in intraosseous pressure induced by tumors inoculated into mouse tibiae was sufficient to increase the expression of pro-metastatic cytokine CCL5." (PMID 35402411, 2022). "CCL5/CCR5 is a biomarker for poor prognosis of pancreatic cancer, prostate cancer, lung cancer, and ovarian cancer." (PMID 35296026, 2022). "One study demonstrated that inhibition of CSC-specific POSTN and its related pathways or the GBM derivative CCL5 disrupted CSC–TAM interaction in mouse models of GBM and prostate cancer." (PMID 35740975, 2022).
prostate carcinoma (continued). "These cells showed increased expression of CCL5, XCL1, and XCL2 in prostate cancer, with the potential to recruit cDC1." (PMID 34936871, 2021). "Therefore, our finding not only identified CCL5 as a potential biomarker for prostate cancer prognosis and metastasis but also suggested that targeting TAMs/CCL5 may represent a potential clinically available strategy for inhibiting PSCSs and prostate cancer metastasis." (PMID 32300100, 2020). "Next, we examined the effect of IL-6, IL-8, CCL5, and FGF2 in the regulation of ERG expression by adding them to the culture media of prostate cancer cells, respectively." (PMID 33425737, 2020). "Both ligand CCL5 and its receptor CCR5 have been suggested as potential therapeutic targets in various cancers, including glioblastoma, breast and prostate cancer, and impairing disease progression." (PMID 32545571, 2020). "Further investigation revealed that the exerted pressure induced osteocyte expression, and through bone matrix remodeling effector C-C motif chemokine ligand 5 (CCL5), and MMPs, promoted the growth of prostate cancer bone metastases." (PMID 31330786, 2019). "Taken together, these results indicate that AP-1 and NF-κB play a central role in the transactivation of scf, ccl5 and ccl11 induced by PKD2 or PKD3 in prostate cancer cells." (PMID 30841931, 2019). "The pro-inflammatory chemokines, including Chemokine (C-C motif) ligand 5 (CCL5 /RANTES), stromal cell derived factor-1 (SDF-1/ CXCL12), and monocyte chemoattractant protein-1 (MCP-1/ CCL2), are often highly expressed in prostate cancer." (PMID 29268703, 2017). "This latter point is particularly relevant, because the prostate has frequently been shown to contain sites of inflammation, and prostate cancer expresses high levels of pro-inflammatory stimuli, including CXCR4, CCL5, and CCL2." (PMID 23362217, 2013). "A 2013 study on prostate cancer patients showed that the CCL5 serum levels were not different among patients groups: (i) negative prostate biopsy, (ii) initial diagnosis of prostate cancer, and (iii) taxane-resistant groups." (PMID 40076892, 2025). "Recent work in prostate cancer identified that PKD2 or PKD3 knockdown results in decreased expression and secretion of pro-inflammatory chemokines SCF, CCL5 and CCL11 in two prostate cancer cell lines, with the proteins contributing to the chemotactic migration of mast cells in vitro." (PMID 38323010, 2024). "TAMs may also release CCL5, which, through activation of the β-catenin/STAT3 signaling pathway, significantly promoted invasion, metastasis, and EMT in studies using prostate cancer cells." (PMID 38033495, 2023). "CCL5 activates β-catenin/STAT3 signaling to promote the self-renewal and tumor metastasis of prostate CSCs (PCSCs), and its knockdown significantly inhibits the metastasis of prostate cancer and the self-renewal capacity of PCSCs." (PMID 35740975, 2022). "Notably, the significant positive correlations between CCL5 and PCSCs-related proteins including ALDH1A1 (p = 0.0001) and STAT3 (p = 0.0001) were observed in the samples of human prostate cancer tissue microarray." (PMID 32300100, 2020). "The CCL5/CCR5 axis is involved in prostate cancer progression: both molecules are expressed in human prostate cancer cell lines, primary cultures of prostatic adenocarcinoma cells and prostate cancer tissues." (PMID 32630699, 2020). "Herein, we demonstrated that TAMs-secreted CCL5 could significantly promote the migration, invasion, epithelial–mesenchymal transition (EMT) of prostate cancer cells as well as the self-renewal of PCSCs in vitro." (PMID 32300100, 2020). "CCR5 antagonist anibamine inhibited prostate cancer cell line growth with and without CCL5 stimulation in vitro, and decreased prostate cancer xenograft growth." (PMID 32630699, 2020).
prostate carcinoma (continued). "In prostate cancer cells with overexpressed with PKD2 and PKD3, ELISA and RT-qPCR assay demonstrated that Erk specific inhibitor PD98059 (PD) antagonized the upregulation of SCF and CCL5 expression induced by PKD2 or PKD3 in DU145 cells." (PMID 30841931, 2019). "Moreover, PKD2/3 depletion not only reduced SCF, CCL5 and CCL11 expression in prostate cancer cells but also inhibited angiogenic factors in MCs." (PMID 30841931, 2019). "Taken together, these data suggested that PKD2/3-regulated SCF, CCL5 and CCL11 secretion in prostate cancer cells may be the key factors that mediated migration and recruitment of MCs in tumor microenvironment." (PMID 30841931, 2019). "To further clarify whether PKD2/3 mediated chemotactic migration of MCs through upregulation of SCF, CCL5, and CCL11 in prostate cancer, we performed migration assay for P815 MCs in a transwell plate." (PMID 30841931, 2019). "Given that multiple autocrine or paracrine chemokines such as SCF, CCL5 and CCL11 mediated MCs migration and recruitment, so we verified whether PKD2 or PKD3 could regulate these chemokines expression in the prostate cancer cells." (PMID 30841931, 2019). "To examine whether Erk1/2 signaling is required for PKD2/3 induced -SCF, CCL5, and CCL11 expression in tumor cells, we first analyzed the interaction of endogenous PKD2 or PKD3 with Erk1/2 in prostate cancer cells." (PMID 30841931, 2019). "Both CCL5 and its CCR5 are expressed in prostate cancer cells." (PMID 30200999, 2018). "In view of the in vitro findings that CCL5/CCR5 signaling and autophagy play an important role in cell invasion, we used orthotopic xenograft models to explore the effect of CCL5/CCR5 and autophagy inhibition on the metastasis potential of prostate cancer." (PMID 30200999, 2018). "Our results demonstrated that DT could reduce the secretion of chemokines, including CCL2, CCL5, and ICAM-1, in prostate cancer cells, and inhibit prostate cancer cell migration under the macrophages’ cultured medium." (PMID 28157698, 2017). "Additionally, prostate cancers typically express high levels of pro-inflammatory chemokines, including CXCL12 (SDF-1), CCL5 (RANTES), and CCL2 (MCP-1)." (PMID 23362217, 2013). "Nevertheless, the mechanism of CCL5 in prostate cancer has not been studied very well." (PMID 33442423, 2021). "Altogether, these results validated that TAMs-secreted CCL5 could promote the invasion and the PCSCs subpopulation of prostate cancer cells in vitro independent of AR status." (PMID 32300100, 2020). "Given CCL5 is highly expressed by TAMs rather than prostate cancer cells, the combinational therapeutic strategy of blocking TAMs and neutralizing CCL5 may be a promising and powerful approach for PCSCs elimination in the future." (PMID 32300100, 2020). "CCL5 could significantly promote STAT3 expression, phosphorylation as well as its nuclear translocation in both DU145 and PC3 cells, indicating that CCL5 could induce persistent activation of STAT3 signaling in prostate cancer cells." (PMID 32300100, 2020). "Further studies identified TAMs rather than prostate cancer cells as the major source of CCL5." (PMID 32300100, 2020). "Serum CCL5 levels do not differ among prostate cancer patients with or without paclitaxel resistance but the expression of the CCR1 receptor increases in paclitaxel-resistant PC3 prostate cancer cells." (PMID 24523569, 2014). "The distinct functions of the two MAPKs may well be reproduced also in prostate cancer cells, as evidenced by our results with the inhibitors PD98059 and SB202190, thus suggesting that also in LNCaP cells p38 MAPK exerts a wider role than ERK1/2 on IL-6 and CCL5 transcription factors." (PMID 19242540, 2009). "Moreover, we present a novel finding related to the ability of CCL5 to induced proliferation in LNCaP cells thank to the activation of STAT5 and the consequent increase of expression of cyclin D1, a pathway controlling cell growth in normal and prostate cancer cells." (PMID 19242540, 2009).